TNF (tumor necrosis factor)
Diseases named in the same sentence as TNF in open-access papers (continued):
Sharing a sentence is not in itself a finding about the gene and the disease.
gastric ulcer (continued). "In particular, the mRNA expression of IL-6 and TNF-α in the DOP-200 and DOP-400 groups was significantly decreased, indicating that these groups could effectively inhibit the further deterioration of gastric ulcers." (PMID 38398633, 2024). "In a mouse study of ethanol-induced gastric ulcers, COST administration declined the TNF-α levels." (PMID 37736519, 2023). "In a further study, manuka honey was also effective against chronic acetic acid-induced gastric ulcers, and the observed effect was due to antioxidant and anti-inflammatory effects with a significant reduction in mucosal MDA levels, TNF-α, IL-1β, and IL-6 and an increase in IL-10 levels." (PMID 38045104, 2023). "Furthermore, treatment with SGD significantly increased the levels of EGF, PGE2, SOD, and Bcl-2 and decreased the levels of TNF-α, TBARS, and caspase-3 in the gastric tissue of rats with ethanol-induced gastric ulcers." (PMID 35449820, 2022). "The results of this study showed that MOE could inhibit the levels of proinflammatory cytokines (TNF-α, IL-1β, IL-6) induced by ethanol, suggesting that MOE has an anti-inflammatory effect on ethanol-induced gastric ulcer." (PMID 34159200, 2021). "Also, alcohol triggers the release of other inflammatory mediators and cytokines such as TNF-α and INF-γ, which further aggravate gastric ulceration." (PMID 33521129, 2021). "However, the levels of TNF-α, IL-1β and IL-6 in tissue and GES-1 cell supernatant were significantly decreased, and the corresponding gastric ulcer and mucosal integrity were improved in the Ran and F-AOH groups." (PMID 32871094, 2020). "Surprisingly, the expression of TNF- α was reduced and that of eNOS was elevated to a marked degree in the PLN-treated rats versus the PPE-treated rats, revealing a rapid and prominent effect of nanoparticles in promoting the healing of a gastric ulcer (p = 0.015 and p = 0.002; respectively)." (PMID 33833690, 2021). "It reduced gastric ulcers (GU) by suppressing ethanol-induced nuclear factor-κB (NF-κB) activity and decreasing the levels of nitric oxide (NO), malondialdehyde (MDA), tumor necrosis factor-α (TNF-α), interleukin-6 (IL-6), interleukin-8 (IL-8), and myeloperoxidase (MPO)." (PMID 34769415, 2021). "The ethanolic extract from M. maderaspatana was able to reduce gastric mucosal lesions, malondialdehyde (MDA) and TNF-α levels, while increased gastric juice mucin content and gastric mucosal catalase (CAT), nitric oxide and PGE2 levels in rats with indomethacin-induced gastric ulcer." (PMID 30018251, 2018). "Pro-inflammatory cytokines like tumor necrosis factor-α (TNF-α), Interleukin-1β (IL-1β), Interleukin-6 (IL-6) and growth factors including insulin like growth factor-1 (IGF-1) play an important role in the pathogenesis of chronic diseases like autoimmune diabetes and gastric ulcers." (PMID 24192345, 2013).
neuroblastoma (129 papers, 2010 to 2026). Neuroblastoma (NB) is the most common solid, extracranial childhood tumor. "We identified a possible association between the TNF-α genetic polymorphisms -238 G/A rs361525 and -308 G/A rs1800629 and the risk of neuroblastoma." (PMID 39408920, 2024). "A previous study reported that TNF-α promotes FasL expression and causes the acceleration of caspase-3-dependent apoptosis in neuroblastoma cells." (PMID 32455774, 2020). "We report that TNF-α causes cell death in human neuroblastoma (NB) cells through NFAT activation and upregulation of FasL protein." (PMID 21298033, 2011). "For example, in neuroblastoma cells, a single 5-minute pulse of TNF can initiate transcription of NF-κB-regulated early response genes that persist for hours, but not late response genes that require either constant or repeated cytokine stimulation." (PMID 40781077, 2025). "We evaluated the expression of HERVs (HERV-K env, HERV-K gag, HERV-W env, and HERV-H env) and cytokine gene expression (IL-1, IL-6, and TNF-α) in neuroblastoma (SH-SY5Y), HEp-2, and Caco-2 cell lines under simulated μg and 1g conditions." (PMID 40143237, 2025). "We found a significant difference (p < 0.001) in TNF-α serum levels between patients with neuroblastoma and the control group." (PMID 39408920, 2024). "Treatment with TNFα enhanced cisplatin cytotoxicity in neuroblastoma cells, most likely through the activation of NF-κB which in turn induced transcription of Fas and hence apoptotic signaling." (PMID 37891379, 2024). "The Western blots of 1 h of LPS stimulation in both neuroblastoma cells exhibited increased TNF-α protein expression compared with the vehicle-treated control." (PMID 38671881, 2024). "When macrophages are co-incubated with a CD99-negative Kelly neuroblastoma cell line and incubated with both antibodies, there is little change in TNF-α decline." (PMID 38534214, 2024). "At shorter timescales, when two pulses of TNF-α were introduced to human neuroblastoma cells within 100 min, the second pulse of TNF-α produced a minimal NF-κB response, revealing a refractory period after the first stimulation." (PMID 38040923, 2023). "Hypoxia, common in cancer due to insufficient oxygen supply, upregulates membrane-bound TNFα on neuroblastoma cells, triggering TAMs to produce CCL20." (PMID 38087370, 2023). "When TNF-α pulses were introduced at low frequency ( ~ 200 min period between pulses) to neuroblastoma cells, full amplitude NF-κB responses continued even after 8 h72." (PMID 38040923, 2023). "Using mouse neuroblastoma cell lines, the administration of ketamine provided an anti-inflammatory effect on the lipopolysaccharide (LPS)-induced production of TNF-α through the inhibition of NF-κB and inducible nitric oxide synthase pathways." (PMID 36765695, 2023). "IL-1β and TNFα from these macrophages stimulated arginine metabolism in neuroblastoma cells, promoting tumor cell proliferation." (PMID 38087370, 2023). "The human neuroblastoma SH-SY5Y cells were subjected to TNFα-mediated necroptosis using conventional stimuli: TNFα (20 ng/mL), Smac mimetic (100 nM), and ZVAD-FMK (20 μM), abbreviated as TSZ." (PMID 37904209, 2023). "Currently, ELISA analysis indicated that propofol treatment suppressed inflammation in neuroblastoma cells exposed to MPP+ by decreasing the levels of TNF-α and IL-1β." (PMID 35350655, 2022). "Our previous studies showed that reactive oxygen species (ROS) and inflammatory cytokines, such as TNF-α, IL-1β, and IL-6, induced FtMt expression in the human neuroblastoma cell line IMR-32." (PMID 35008961, 2022). "Butyrate has been demonstrated to have neuroprotective effects against brain injury and TNF-α-induced SH-SY5Y (Human Neuroblastoma Cell Line) neuronal cell death." (PMID 36670866, 2022).
neuroblastoma (continued). "In this study, we explored the effects of glucose on human SH-SY5Y neuroblastoma cells in the presence of a proinflammatory mediator, tumor necrosis factor-alpha (TNF-α), which correlates with neuropathic pain in constrictive neuropathy." (PMID 35743863, 2022). "Previous investigations have reported that rutin inhibits the production of proinflammatory cytokines in microglia by lowering TNF-α and IL-1β levels in human neuroblastoma ( SH-SY5Y ) cells." (PMID 36139918, 2022). "TRIM32 overexpression promotes cell proliferation, transforming activity, cell motility and prevents apoptosis, but it is also shown to promote asymmetric cell division of neuroblastoma cells and to enhance TNFα-induced apoptosis." (PMID 33999923, 2021). "In contrast, BNIP3-mediated mitophagy was also shown to protect neuroblastoma SH-SY5Y cells against TNF-α-induced death." (PMID 33879840, 2021). "A recent study showed that macrophage-derived IL-1 and TNF-α regulated arginine metabolism in neuroblastoma cells through a signaling pathway dependent on RAC-alpha serine/threonine-protein kinase (AKT)." (PMID 32983125, 2020). "We also demonstrated that FTMT expression was increased in response to TNF-α via NF-κB activation in the human neuroblastoma cell line IMR-32." (PMID 32455741, 2020). "CCL2 was also found to promote apoptosis and secretion of TNF-α and IL-1β in neuroblastoma SH-SY5Y cells and inhibit cell viability, while the knockdown of CCL2 exerted the opposite effects." (PMID 30761072, 2019). "In this study, we examined the individual and combined effect of IFN-γ and TNF-α on cell death and expression of Par-4, along with its interacting proteins in human neuroblastoma cells." (PMID 29278364, 2017). "Taken together, this in vitro in vitro and clinical data confirms that co-expression of IFN-γ and TNF-α enhances the expression of Par-4 that gives beneficial survival rates in Neuroblastoma patient." (PMID 29278364, 2017). "The resistance of neuroblastoma cells to apoptosis induced by TNF, tumor necrosis factor-related apoptosis-inducing ligand (TRAIL), and cytotoxic agents such as doxorubicin, has been attributed to a lack or diminished expression of caspase-8." (PMID 29278364, 2017). "The study concludes that a combinatorial approach using IFN-γ and TNF-α can be explored to maximize the effect in chemotherapy in neuroblastoma, and implies a role for Par-4 in the process." (PMID 29278364, 2017). "After treating with Aβ1–42 for 6 h, PGC-1α prevents neuroblastoma cells from death and largely reduces the level of IL-1β and TNF-α." (PMID 28946859, 2017). "This promising effect of AITC in controlling JNK/NF-κB/TNF-α cross-linking maintains the Bcl-2 gene family and protects neuroblastoma cells from activated microglia-induced toxicity." (PMID 28671636, 2017). "In the following we analyzed if TNF-α is crucial for LCL161-mediated sensitization for VCR in neuroblastoma." (PMID 29152118, 2017). "In conclusion, the present data suggests that though human neuroblastoma cells are resistant to IFN-γ and TNF-α, a combination of these cytokines strongly exert cytotoxic effects in neuroblastoma cells." (PMID 29278364, 2017). "Unbiased transcript analysis for IFN-γ, TNF-α, and Par-4 were analyzed from three independent clinical datasets from neuroblastoma patients." (PMID 29278364, 2017). "Treating neuroblastoma cells with TNF-α resulted in the activation of nuclear factor-kappa B (NF-κB) and subsequently, the translocation of NF-κB from the cytoplasm to the nucleus." (PMID 25503960, 2015). "In the present study, the inflammatory cytokine, tumor necrosis factor-α (TNF-α) upregulated CXCR4 expression in neuroblastoma cells and increased migration to the CXCR4 ligand SDF-1α." (PMID 25503960, 2015). "TNF-α was also shown to induce CXCR4 expression in neuroblastoma cells in a time- and dose-dependent manner." (PMID 25503960, 2015).
neuroblastoma (continued). "Exposure to TNF-α increased IκB-α phosphorylation levels in the neuroblastoma SH-SY5Y cell lines, which was accompanied by a marked decrease in IκB-α protein expression." (PMID 25503960, 2015). "Taken together, these findings led to the conclusion that TNF-α partially functions through the NF-κB signaling pathway to upregulate CXCR4 expression to foster neuroblastoma metastasis." (PMID 25503960, 2015). "There was another clear upregulation of CXCR4 expression in SH-SY5Y cells following co-culture with macrophages, an alternative source of TNF-α in the neuroblastoma microenvironment." (PMID 25503960, 2015). "TNFα paralyzed actin filament reorganization in neuroblastoma cells due to oxidative damage, whereas physiological levels of ROS intermediates seem to be necessary for proper growth cone motility." (PMID 25050325, 2014). "Irreversible oxidative damage (carbonylation) to actin was detectable in neuroblastoma cells exposed to TNFα." (PMID 25050325, 2014). "Mechanisms of TNF-α-induced neurotoxicity have been repeatedly investigated using the closely related SH-SY5Y human neuroblastoma cell line." (PMID 24602263, 2014). "Previous studies in chick cortical neurons and human SH-SY5Y neuroblastoma cells demonstrated superoxide production in response to TNFα utilizing dihydroethidium oxidation or a SOD-inhibitable cytochrome C oxidation as demonstrated." (PMID 25050325, 2014). "We show here that exposure of a human neuroblastoma cell line (SK-N-MC cells) to TNF-α promotes ROS-mediated caspase-1 activation and IL-1β secretion." (PMID 23940760, 2013). "Here we report that TNF and ceramide exert dose-dependent cytotoxic effects on DA neuroblastoma cells and primary DA neurons." (PMID 22973882, 2012). "To perform quantitative analysis of complex sphingolipids and sphingoid bases in MN9D ventral mesencephalon DA neuroblastoma cells in response to TNF (10 ng/mL) treatment, we employed a lipidomics approach based on previously published protocols." (PMID 22973882, 2012). "In agreement with results obtained in TNF-treated microglia and macrophages, QPCR analysis revealed that TNF treatment induced downregulation of Parkin mRNA in primary dopaminergic neuroblastoma cells." (PMID 21858193, 2011). "Recently, it has been shown that WNV induced the expression of IL-1β, -6, -8, and tumor necrosis factor (TNF)-α in human neuroblastoma SK-N-SH cells in a dose- and time-dependent manner, which coincided with an increase in virus-induced cell death." (PMID 21994755, 2011). "To test this directly, we treated neurally differentiated ventral mesencephalon MN9D neuroblastoma cells with 10 ng/mL TNF and harvested the cells for RNA extraction after 6, 12 or 24 hours of stimulation." (PMID 21858193, 2011). "In NCT03294954, GD2-CAR-iNKTs are infused with etanercept, an anti-TNF antibody, based on the observation that TNF promoted tumor progression while inhibition of TNF signaling improved outcomes in murine xenograft models of neuroblastoma." (PMID 41000376, 2025). "An increase in IL-6 and TNF-α has also been observed in vitro studies with the SH-SY5Y undifferentiated human neuroblastoma cell line when exposed to OTA (3.1–12.5 μM) for 24–48 h, with a dose-dependent increase in the TNF-α response after 48 h, as also seen in 3D rat whole-brain aggregate cultures." (PMID 40559842, 2025). "Although the concentrations of human exposure to CT vary, our data suggest that even at low concentrations of acute exposure to MC-LR, NOD, CYN, and BMAA change cell metabolic activities, increase inflammatory IL-6, SOD1, and TNFα gene expression, and cytotoxicity in neuroblastoma cells." (PMID 41424770, 2025). "Single in vitro study reports a neuroprotective action of low silicon concentrations on human SH SY5Y neuroblastoma cell lines by inducing an anti-apoptotic effect and anti-inflammatory reaction as a result of diminishing the level of tumor necrosis factor TNF-α." (PMID 38495942, 2024).
neuroblastoma (continued). "Since Voeller and colleagues already described synergy between CD40 agonists and anti-GD2 therapy in neuroblastoma, the addition of TNF and CD40 agonists to the treatment regimen could prove a promising new strategy." (PMID 38087370, 2023). "In addition, in vitro studies on JEV-infected human neuroblastoma cells have shown impaired β-oxidation of long-chain fatty acids (PUFAs) and increased expression of interleukin 6 (IL-6) and tumor necrosis factor α (TNF-α)." (PMID 37775774, 2023). "Additionally, incubating neuroblastoma cell lines with human monocytes increased IL-1β and TNFα-expressing macrophages, signifying an M1 phenotype via AKT phosphorylation." (PMID 38087370, 2023). "The radiation-induced cross effect of TNFα-NFκB promotes the survival of neuroblastoma cells." (PMID 36437984, 2022). "To test whether NCS1 is regulated by NFκB, we treated SHSY5Y human neuroblastoma cells with TNF‐α and consequently measured NCS1 protein expression." (PMID 32239615, 2020). "Furthermore, we demonstrated that the pro-inflammatory cytokines TNFα and IL-1β as well as serum components stimulate chemerin secretion by neuroblastoma cells." (PMID 29221117, 2017). "Finally, we also confirm that the gene expression profile of IFN-γ and TNF-α together synergistically correlate with the expression of Par-4 in human neuroblastoma patients." (PMID 29278364, 2017). "Finally, we identified similar synergistic patterns of IFN-γ and TNF-α expression with Par-4 transcripts in human neuroblastoma patients." (PMID 29278364, 2017). "In neuroblastoma we could discriminate three different tumor cell types as well, based on their TNF-α sensitivity and modulation of NF-κB pathways in response to LCL161." (PMID 29152118, 2017). "Stimulation of neuroblastoma cells with serum, TNFα or IL-1β increased chemerin secretion." (PMID 29221117, 2017). "TNFα and pan-caspase inhibitors could both reverse the anti-neuroblastoma effect induced by macrophages." (PMID 26286454, 2015). "The present data suggests that the TNF-α-activated NF-κB/CXCR4/SDF-1α pathway may be a potential regulator of neuroblastoma cell metastasis." (PMID 25503960, 2015). "Furthermore, the inflammatory cytokine TNF-α acts as a regulator of functional CXCR4 expression on neuroblastoma cells in a NF-κB-dependent manner." (PMID 25503960, 2015). "Earlier studies in neuroblastoma cells revealed oxidative damage to actin due to TNFα exposure." (PMID 25050325, 2014). "In the current study, we demonstrated that hBDNF expressed from LV-transduced cells conferred significant neuroprotection (p<0.01) against a pro-inflammatory cytokine TNF-α in several human neuronal cell cultures including neuroblastoma HTB-10 and monocytic U937 cells." (PMID 24505242, 2014). "Prolonged bath application of TNFα or IL-1β (6–8 h) to dissociated SC neurons or SC explants stunted neurite outgrowth in a dose-dependent manner in accordance with previous findings in hippocampal neurons or neuroblastoma cells." (PMID 25050325, 2014). "In this study, we investigated the role of neuronal RNF11 as a component of the A20 ubiquitin-editing complex in regulating TNF-α-induced canonical NF-κB activity by targeted knockdown of endogenous RNF11 in human neuroblastoma cells and primary neuronal cultures." (PMID 22507528, 2012). "Therefore, we investigated the effect of WNV infection on the expression of key pro-inflammatory cytokines such as IL-1β, -6, -8, -18 and TNF-α in human neuroblastoma cell line SK-N-SH at both mRNA and protein levels." (PMID 21034511, 2010). "Our results suggest that the serum levels of pro-inflammatory cytokines IL-6, IL-8, IFN-γ and TNF-α could be an immunological biomarker contributing to our understanding of the pathogenesis of neuroblastoma with prognostic potential in Mexican pediatric patients with NB." (PMID 40722593, 2025). "Additionally, ARID3B induces TNF induced death and promotes neuroblastoma and ovarian tumor growth." (PMID 26121572, 2015).